IL18 (interleukin 18)
Diseases named in the same sentence as IL18 in open-access papers (continued):
Sharing a sentence is not in itself a finding about the gene and the disease.
COVID-19 (continued). "Of the tested inflammatory cytokines/chemokines, only a few significant associations were found with COVID-19 severity: lower levels of IL-1β, IL-33 together with significantly higher levels of IL-18 were found in women with moderate/severe COVID-19 as compared to asymptomatic/mild cases." (PMID 40303405, 2025). "Reverse causality of COVID-19 with 3 suggestively related inflammatory proteins IL-10, IL-18, and PD-L1 showed none to be significant (P > .05)." (PMID 40101060, 2025). "Specifically, higher levels of IL-1β, IL-6, IL-8, IL-10, IL-18, and TNFα have been found in patients with severe disease and complications, such as acute respiratory distress syndrome (ARDS), which are the main cause of mortality in COVID-19." (PMID 40788382, 2025). "IL-18, IL-1β, and IL-23 have been correlated with arginine biosynthesis in COVID-19." (PMID 41002992, 2025). "Additionally, the predictive power assessed by the AUC curve showed that IL15RA (AUC=0.842), SLAMF1 (AUC=0.775) and IL18 (AUC=0.775) as the top three proteins predicting critical COVID-19 illness." (PMID 40475767, 2025). "Given its immunopathogenic role, IL-18 may be considered as a promising biomarker of COVID-19 severity, and therapeutic strategies targeting IL-18 inhibition, such as neutralization with IL-18 binding protein, may offer clinical benefits in severe cases." (PMID 40788382, 2025). "Moreover, NLRP3 inflammasome products, such as IL-1β and IL-18, are increased in patients with severe acute COVID-19 and positively correlated with adverse clinical outcomes." (PMID 39012668, 2024). "Although IL-1β and IL-18 levels in the plasma and lungs correlate with severe COVID-19 (5, 7, 33, –, 35), whether these inflammatory cytokines restrict viral replication and the consequence of inflammasome activation in the lung have not been clarified." (PMID 39240187, 2024). "Therapeutic interventions targeting IL-18 and IL-1β signaling pathways are being studied to alleviate cytokine-driven pathological processes and are expected to improve the clinical prognosis of patients with COVID-19." (PMID 38399989, 2024). "The fourth is pathway is through cytokine storm: in COVID-19, the cytokine storm is characterised by an excessive production of pro-inflammatory cytokines such as IL-6, IL-1, IL-18, and granulocyte-macrophage colony-stimulating factor (GM-CSF), particularly in severe instances." (PMID 38214889, 2024). "However, the excessive or dysfunctional release of IL-18 and IL-1β leads to excessive inflammation, exacerbates tissue damage, and leads to cytokine storms observed in severe COVID-19 cases." (PMID 38399989, 2024). "First, we identified six cytokines and chemokines, including HGF (significant difference in cohort 1 and cohort 4) and IL-10, IP-10, SCGF-β, IL-16, and IL-18 (significant difference in cohort 3 and cohort 4), that consistently showed variations in COVID-19 in different cohorts." (PMID 38710800, 2024). "Furthermore, autoimmune diseases can be triggered by COVID-19 in genetically predisposed patients, following the activation of an aberrant immune response by the cytokine cascade (TNF-α, IL-6, IL-1β, IL-17, and IL-18) induced by SARS-CoV-2." (PMID 38707102, 2024). "In addition to the high levels of IL-18, IL-1R7 is also found to be highly expressed in cell-to-cell communication among immune cells in COVID-19 patients and an elevated IFNγ was also observed." (PMID 38983847, 2024). "In addition, IL-18 can be used as a biomarker to distinguish active adult-onset Still's disease (AOSD) from COVID-19; IL-18 is 68-fold higher in patients with active AOSD than in those with severe COVID-19." (PMID 38328001, 2024). "In addition to cytokines whose expression increased with the progression of COVID-19, IL-16 and IL-18 were the only two cytokines whose expression decreased significantly with the worsening of the disease." (PMID 38710800, 2024).
COVID-19 (continued). "To determine the biomarker reliability of the inflammasome signaling proteins caspase-1, ASC, IL-1β and IL-18, we plotted ROC curves for each protein using data from healthy subjects and from patients that tested positive for COVID-19 and presented an active infection." (PMID 37168848, 2023). "In fatal cases of COVID-19, serum IL-18 levels correlated with MAIT cell activation." (PMID 37536148, 2023). "We found that dysfunction of IL-18 negative feedback control is associated with disease severity and death in COVID-19 positive patients from symptom day 15 onwards." (PMID 36823262, 2023). "We analyzed the protein levels of the inflammasome signaling proteins caspase-1, ASC, IL-1β and IL-18 in patients with COVID-19 and patients who had recently recovered from a COVID-19 infection and compared them to the levels in plasma samples from healthy donors, who never had COVID-19." (PMID 37168848, 2023). "Analysis of demographic data and levels of 19 cytokines from 109 individuals diagnosed with COVID-19 revealed that IL-18 was among the top three cytokines that was differentially regulated and significantly elevated in those who died compared to those who survived infection." (PMID 36894537, 2023). "Direct inflammasome inhibition attenuated COVID-19 severity in a preclinical model, but potent forms of such inhibitors are not yet in clinical use, which leaves the option of inhibiting downstream cytokines IL-1β and IL-18." (PMID 37582864, 2023). "IL-18 additionally stimulates interleukin-6 (IL-6) and Granulocyte–macrophage colony-stimulating factor (GM-CSF), blockade of which have yielded therapeutics for severe COVID-19." (PMID 36823262, 2023). "Alternatively, anti-inflammatory treatment for TB-IRIS as well as severe COVID-19 could evaluate the possible role of IL-18 inhibition based on the central role of IL-18 in the immunopathogenesis of both these conditions and preliminary findings." (PMID 36839482, 2023). "When compared to non-infected controls, protein levels of caspase-1, ASC, IL-1β and IL-18 were higher in patients with active (Positive) COVID-19 (median day of blood collection: 11 days) and in patients who recently recovered from COVID-19 (median day of blood collection: 61.5 days)." (PMID 37168848, 2023). "IL-18 participates as an element of inflammasome activation among COVID-19 patients." (PMID 36926338, 2023). "Our observations suggests that IgG G0 abundance (potentially together with IL-18) before vaccination might serve as a biomarker for humoral responses after vaccination for COVID-19 or other infectious diseases." (PMID 37248417, 2023). "In contrast, severe COVID-19 includes sustained expression of these markers with additional signatures including IL-6, IL-10, IL-18, IL-23, TNF, and eotaxin among others suggesting that specific timing and failure to resolve inflammatory responses are important factors in disease progression." (PMID 37491352, 2023). "61.54% of non-survivors (16 out of 26) and 67.02% of survivors from COVID-19 (63 out of 94), can be identified as heterozygous (TG) for the rs1946518 IL-18 polymorphism." (PMID 36999046, 2023). "We showed elevated IL-18 in the serum of patients with COVID-19." (PMID 36899824, 2023). "While causation cannot be established in this observational study, our findings provide hypothesis-generating evidence for modulation of IL-18 from symptom day 15 onwards in patients with COVID-19." (PMID 36823262, 2023). "In addition, enhanced plasma levels of pyroptosis markers were detected in COVID-19 patients, and the levels of caspase -1 and IL-18 in serum correlated with the degree of COVID-19 severity, particularly in elderly patients." (PMID 38439942, 2023). "Moreover, glycosylation of IgM correlates with circulating immune cell glycosyltransferase expression of ST3GAL4 and MAN1A2, previously reported clinical markers of COVID-19 severity, and elevations in cytokines IL-16 and IL-18." (PMID 37398192, 2023).
COVID-19 (continued). "Finally, interleukin-18 is a highly predictive biomarker of death by COVID-19, and measurements in bronchoalveolar lavage fluid (BALF) showed a significant increase in the interleukin-1β (IL-1β) level in patients with moderate to severe COVID-19." (PMID 37476705, 2023). "However, a previous report has shown that caspase-1 and IL-18 in serum correlate with COVID-19 severity." (PMID 37168848, 2023). "Interestingly, CD69 expression on MAIT positively correlated with the level of plasmatic IL-18 that was significantly higher in the plasma of long-term ICU patients with fatal COVID-19 compared to plasma from patients hospitalized in an ICU or IDU." (PMID 35159352, 2022). "Adding to that evidence the increased expression of both IL-1β and IL-18, as inflammasome activation products and as inflammasome complex upregulators, corroborate our hypothesis of its activation in COVID-19." (PMID 36361818, 2022). "IL-18 was significantly increased only in moderate COVID-19 patients." (PMID 35663992, 2022). "COVID-19 is associated with cytokine storm with exaggerated inflammatory response characterized by release of large amounts of cytokines like IL-1b, IFN-α, IFN-γ, TGF-α, IL-6, IL-12, IL-18, and IL-33." (PMID 35382491, 2022). "A striking phenotype perturbation of Tregs showing the over-expression of pro-inflammatory cytokines, such as Treg COVID-19 phenotype-inducers, interleukin (IL)-6 and IL-18 were found in severe COVID-19 cases compared with mild cases, recovered patients, and healthy donors." (PMID 36069182, 2022). "In addition, we found diffuse myocardial CD68+ cell infiltration in the patient biopsy sample, suggesting an increased level of IL-18 produced by monocytes and macrophages in the heart with COVID-19 vaccine-related myopericarditis." (PMID 35251049, 2022). "Severe COVID-19 patients have been shown to have an imbalance of IL-18/IL-18BP." (PMID 36238287, 2022). "Thus, elevated IL-18 production by circulating or heart-infiltrating monocytes and macrophages could directly cause cardiomyocyte injury in the patient with myopericarditis after COVID-19 vaccination, which was proven by high cardiac troponin levels and decreased left ventricular systolic function." (PMID 35251049, 2022). "Infection with SARS-CoV-2 leads to COVID-19, the severity of which is partly due to host immune responses, including the release of proinflammatory cytokines, such as interleukin (IL)-6, IL-18 and tumor necrosis factor (TNF), with serious biological and clinical consequences." (PMID 35336907, 2022). "An investigation found a higher expression of IL-16, IL-7, ILCs, and IL-18 in males with COVID-19 than in females, which may promote COVID-19-related cytokine storms." (PMID 35664675, 2022). "In addition to IL-1β, circulating levels of IL-1Ra, IL-18 and IL-18 binding protein (IL-18BP) are increased in hospitalized COVID-19 patients." (PMID 36209522, 2022). "Among these cytokines, IL-18 appears to have a special role as it can be released by activated macrophages and neutrophils and, thus, combined with IL-12, could contribute to COVID-19 fatality." (PMID 35386707, 2022). "Cut-off values and ORs (95% CI) for the risk of developing severe/critical COVID-19 in the univariate and multivariate analyses for News-2, Ferritin, CRP and NLR (model 1), for the cytokines sCD25, IL1Ra and IL18 (model 2) and for activated CD4 and CD8, NK, Tc2 and EMRA CD8 (model 3)." (PMID 35425776, 2022). "Next, we tested whether monocytes in the patient with myopericarditis after COVID-19 vaccination are activated to produce IL-18." (PMID 35251049, 2022). "IL-1β and IL-18 are direct results of inflammasome activation, our analysis showed that they were increased in the COVID-19 group when compared to the control (p < 0.0005) group and that IL-18 was increased in the COVID-19 group even when compared to the H1N1 group (p < 0.0001)." (PMID 36361818, 2022).
COVID-19 (continued). "The findings of the present study shed light on the role of IL-18 in COVID-19 pathogenesis and might provide evidence for clinical trials on IL-18 antagonists for the treatment of severe patients with COVID-19." (PMID 35930243, 2022). "In this view might be of a certain interest that IL-18 levels are considered useful markers of ARDS in COVID-19 and other clinical conditions." (PMID 36551320, 2022). "Many papers have addressed the association of elevated plasma IL-18 level with mortality in ARDS, emphasizing the connection between NLRP3 inflammasome and COVID-19 progression." (PMID 36052163, 2022). "In IL-18-injected mice, we found NK cell infiltration in the myocardium near the pericardium, where inflammation or cardiomyocyte damage likely occurred in the patient with myopericarditis after COVID-19 mRNA vaccine." (PMID 35251049, 2022). "These subsets expressed the amphiregulin (AREG), epiregulin (EREG), and cytokine interleukin-18 (IL-18) genes and appeared to exhibit profibrogenic and proinflammatory features, suggesting that they may be potential targets for COVID-19 treatment." (PMID 36298825, 2022). "This study shows that elevated IL-18 predicts poor prognosis in critically ill COVID-19 patients." (PMID 36111789, 2022). "This study also showed the association of neuroaxonal damage markers 14-3-3 and NfL, and proinflammatory cytokines IL-18, IL-1RA and IL-8 with COVID-19 severity in the acute phase, and interestingly, the significant association of CSF 14-3-3 and CSF NfL levels with the long-term functional outcome." (PMID 35479062, 2022). "This study aims to investigate the associations of plasma LIGHT and another potentially targetable cytokine, interleukin-18 (IL-18), with ARDS, acute hypoxic respiratory failure (AHRF), or acute kidney injury (AKI), caused by non-COVID-19 viral or bacterial sepsis." (PMID 35203474, 2022). "The mRNA expression of the products of the inflammasome activation, such as IL-1β and IL-18, was overexpressed in COVID-19/B.1 patients (p < 0.0001 vs. control patients) and overexpressed in COVID-19/B.1.1.7 (p < 0.0001 vs. COVID-19/B.1 patients)." (PMID 36498845, 2022). "Previously it has been demonstrated that in the general population with COVID-19, men have increased plasma levels of innate immune cytokines such as IL-8 and IL-18 along with more robust induction of monocytes, whereas women show more robust T cell activation compared with men2." (PMID 36289317, 2022). "The inflammasome (NLRP3, associated with IL-18 activation) was reported to be activated during SARS-CoV-2 infection and has been proposed as an indicator of COVID-19 disease severity, predicting the release of pro-inflammatory cytokines that lead to dysregulated immune responses and tissue damage." (PMID 36359755, 2022). "A previous study using an animal model of acute respiratory distress syndrome (ARDS), that is frequently diagnosed in critical COVID-19 cases, demonstrated that serum levels of IL-18 could serve as a biomarker of severity and mortality." (PMID 35386707, 2022). "For the majority of these cytokines and chemokines, including those that are typically associated with macrophage activation syndrome (IL-6, IL-18, IFN-γ, TNF-α, CXCL9), the increase was less pronounced in COVID-19 critical condition than in macrophage activation syndrome patients." (PMID 35645351, 2022). "For example, higher levels of IL18 were markers of poor prognosis in COVID-19 patients." (PMID 36613555, 2022). "In COVID-19 patients, IL-18 has been studied for its role as a component of inflammasomes." (PMID 36111789, 2022). "Furthermore, the downstream factors of TLR7 and BTK in TLR pathway, such as MYD88, IRF7, NFKB1, and JUN, and cytokines (TNF, IL1B, and IL18) were elevated in men with severe COVID-19." (PMID 34330889, 2021). "Furthermore, in a study of a small number of children with pediatric multisystem inflammatory syndrome or COVID-19, plasma IL-18 levels were increased in addition to IL-6 levels." (PMID 33841434, 2021).
COVID-19 (continued). "Of note, the levels of IL-1β in COVID-19 patients were comparable to those seen in monogenic autoinflammatory disorders of IL-1β excess, whereas the levels of IL-18 were lower in COVID-19 patients relative to the levels observed in autoinflammatory IL-18opathies that predispose to MAS." (PMID 33232303, 2021). "IL-18 was correlated with markers of the severity of COVID-19, such as IL-6 and LDH." (PMID 34539644, 2021). "In this context, given differences in immune response to COVID-19, including for interleukin-18, it might also be worth considering whether the use of these interventions should differ by sex." (PMID 34911594, 2021). "Thus, blocking IL-18 has therapeutic efficacy for AOSD but has yet to be applied to COVID-19 treatment now." (PMID 34948117, 2021). "The proinflammatory Th1 helper (IL-18, IP-10, MIG, and IL-10) and ARDS-associated cytokines (IL-6, MCP-1, IL-1RA, and IL-8) were increased progressively in patients with increasing severity of COVID-19." (PMID 34938289, 2021). "A correlation between IL-18 and COVID-19 severity had only been found in a small study, but a more recent study suggested this cytokine might be of prognostic value." (PMID 34422145, 2021). "Moreover, active AOSD patients had 68-fold higher IL-18 levels and 5-fold higher ferritin levels than severe COVID-19 patients (both p<0.001)." (PMID 34367188, 2021). "IL18 expression was downregulated in Asymptomatic as compared to severe COVID-19 cases." (PMID 34824360, 2021). "Taken together, these studies suggest that IFNγ or its precursors, such as interleukin-18, interleukin-12 or interleukin-23, could have a role in COVID-19." (PMID 34911594, 2021). "We investigated whether a key modifiable interferon precursor, interleukin-18, was related to COVID-19, overall and by severity, using Mendelian randomisation." (PMID 34911594, 2021). "Whilst, ILR1α, IL-1α and IL-18 levels were reduced in Asymptomatic COVID-19." (PMID 34824360, 2021). "In addition, the level of Casp1p20 and IL-18 in COVID-19 patients has been shown as an important marker for determining disease severity." (PMID 33467177, 2021). "COVID-19 patients have inflammasome-dependent pyroptosis and increase in IL-18." (PMID 34151773, 2021). "Particularly, novel anti-human IL1R7 antibodies that block IL18 could be a promising COVID-19 treatment option." (PMID 35145507, 2021). "IL-18 transcription was higher in the COVID-19 SEVERE when compared to COVID-19 MILD." (PMID 34315957, 2021). "Interleukin-18 could be a modifiable target to prevent COVID-19 and should be further explored in an experimental design." (PMID 34911594, 2021). "Previous studies reported that COVID-19 is frequently associated with a massive production of 14 cytokines including IFN-γ, IL-1RA (IL1RN), IL-2RA, IL-6, IL-10, IL-18, HGF, MCP-3 (CCL7), MIG (CXCL9), M-CSF (CSF1), G-CSF (CSF3), MIG-1a (CCL3), CTACK (CCL27), and IP-10 (CXCL10)." (PMID 34262555, 2021). "Indeed, MAS was found to present in some COVID-19 patients and a significantly higher serum IL-18 level was observed in the patients with MAS than patients without MAS." (PMID 33823154, 2021). "Notably, IL-18 expression is dependent on NF-κB signaling, and IL-18 has been shown to correlate with the severity and mortality of COVID-19." (PMID 34578468, 2021). "In our cohort, levels of IL-1β and IL-18 were higher in patients with COVID-19 compared with HVs." (PMID 33232303, 2021). "In addition, high plasma levels of granulocyte macrophage colony stimulating factor, IL-18, C-C motif chemokine 2, C-X-C motif chemokine ligand 10, and osteopontin (OPN) confirmed the importance of monocytes in pneumonia associated with COVID-19." (PMID 34067072, 2021). "Interestingly, our active AOSD patients had 68-fold higher levels of IL-18 than severe COVID-19 patients." (PMID 34367188, 2021).